FOXD3 (forkhead box D3)
Diseases named in the same sentence as FOXD3 in open-access papers (continued):
Sharing a sentence is not in itself a finding about the gene and the disease.
melanoma (continued). "In addition, the ERK1/2/SOX10/FOXD3 axis appears to be specific to mutant BRAF melanoma cells since N-RAS mutant melanoma cells have no detectable level of basal or induced FOXD3 expression." (PMID 29295999, 2018). "While melanoma cell populations that express high levels of RTK may be selected and expand following MAPK inhibitor treatment, FOXD3 is increased by BRAF inhibitor treatment and transcriptionally induces ERBB3 expression, providing an early adaptive resistance response in melanoma." (PMID 26426052, 2015). "The stable or transient knockdown of CD271 in melanoma cells revealed that the NCSC-like phenotype is maintained by expression of CD271 which in turn controls the levels of downstream targets, e.g., SOX10, FOXD3, and SOX2 (not shown)." (PMID 32878000, 2020).
breast carcinoma (12 papers, 2015 to 2024). "Down-regulation of the transcription factor FOXD3 promotes an EMT phenotype in breast cancer cells, causing proliferation and invasion both in vivo and in vitro while overexpression inhibits this phenotype." (PMID 27144453, 2016). "In addition, FOXD3 deficiency was demonstrated to promote breast cancer progression by induction of epithelial-mesenchymal transition." (PMID 27926503, 2017). "FOXD3 is a putative tumor suppressor that affects growth, invasion, metastasis, and angiogenesis of a number of cancers, including neurobastoma 26, breast cancer 27, gastric cancer 28, and the deficiency of FOXD3 expression is linked to their malignant phenotypes." (PMID 28203521, 2016). "Also, FOXD3 deficiency promoted breast cancer EMT and lymph node metastases." (PMID 28430585, 2017). "To further confirm the exact role of FOXD3 in drug resistance, we overexpressed FOXD3 in luminal breast cancer cell lines." (PMID 31937753, 2020). "Furthermore, promoting the expression of FOXD3 is beneficial for the prognosis of patients with neuroblastoma, whereas inhibiting FOXD3 expression is detrimental to the prognosis of breast cancer patients." (PMID 39494294, 2024). "Finally, intersecting specific DMGs of the two patients, we observed common tumor pathways involved in lymphoma and breast cancer including transcription factors and oncogenes (e.g., FOXD3/ESR1/HOXA9/BCL11B)." (PMID 37029309, 2023). "Ectopic expression of FOXD3 stimulated the expression of miR-548d-3p and repressed JUND and RPS6KA2 mRNA expression, as well as greatly enhancing the BET sensitivity of luminal breast cancer cells." (PMID 31937753, 2020).
colon cancer (12 papers, 2013 to 2025). "Although FoxD3 is associated with several cancers, its role in colon cancer and the underlying mechanism are still unclear." (PMID 27926503, 2017). "In addition, comparing colon cancer metastasis and colon cancer cells, numerous DEGs were identified to be associated with the FOXD3 gene." (PMID 37151068, 2023). "The aim of the study was to investigate whether FOXD3 deficiency can influence the growth and apoptosis of human colon cancer cells." (PMID 27926503, 2017). "Given FoxD3’s frequent methylation in colon cancers, it is plausible that the increased expression of DCLK1-S in tissues is due to the downregulation of FoxD3 status in colitis." (PMID 40839695, 2025). "Next, the effects of the FOXD3 on the proliferation and invasion abilities of colon cancer bone metastatic cells were identified using Cell Counting Kit-8 (CCK8) and Transwell cell migration assays, respectively." (PMID 37151068, 2023). "In this study, the results showed that the expression of the FOXD3 gene was altered in various tumor tissues and downregulated in the colon cancer tissues." (PMID 37151068, 2023). "First, the changes in the expression levels of the FOXD3 gene and differentially expressed genes (DEGs) between the colon cancer samples and colon cancer metastases were obtained from The Cancer Genome Atlas (TCGA) database." (PMID 37151068, 2023). "In-vitro experiments were performed to explore the molecular role of the FOXD3 gene in the bone metastasis of colon cancer." (PMID 37151068, 2023). "Analyzing the UALCAN public database indicated that the FOXD3 gene was differentially expressed in various tumor tissues and its relative expression level in colon cancer (n = 286) tissues was lower than that in the normal tissues (n = 41)." (PMID 37151068, 2023). "FOXD3 knockdown activated a key signaling pathway in human colon cancer cells, EGFR-Ras-Raf-MEK-ERK." (PMID 33450835, 2021). "Their findings revealed FOXD3 knockdown considerably enhanced the proliferation and invasiveness of human colon cancer cells." (PMID 33450835, 2021). "While transcriptional repressor FOXD3 is expressed in many types of embryonic cells, its knockdown dramatically increases human colon cancer cell proliferation, affecting the EGFR-Ras-Raf-MEK-ERK signaling pathway." (PMID 30987631, 2019). "A recent study indicates that forkhead box D3 is a tumor suppressor of colon cancer via the inhibition of EGFR/RAS/RAF/MEK/ERK signal pathway." (PMID 30858760, 2019). "FOXD3 knockdown dramatically increased human colon cancer cell proliferation in vitro and in vivo, enhanced cell invasive ability and inhibited cell apoptosis." (PMID 27926503, 2017). "In order to determine the function of FOXD3 in colon cancer, we compared FOXD3 expression levels between colon cancer cells and normal colon cells." (PMID 27926503, 2017). "Meanwhile, FOXD3 knockdown activated EGFR-Ras-Raf-MEK-ERK signaling pathway in human colon cancer cells and caner tissues." (PMID 27926503, 2017). "In order to further confirm that FOXD3 was a suppressor of colon cancer cell proliferation, we performed rescue experiments by transfection of FOXD3 protein into FOXD3 knockdown cells." (PMID 27926503, 2017). "In this study, our results showed that FOXD3 knockdown markedly promoted colon cancer cell proliferation and xenograft tumor formation." (PMID 27926503, 2017). "In conclusion, FOXD3 knockdown results in colon cancer cell proliferation and tumor formation, increased cell invasive ability and decreased cell apoptosis." (PMID 27926503, 2017). "In our study, we demonstrated that FOXD3 knockdown markedly activated EGFR-Ras-Raf-MEK-ERK signaling pathway in human colon cancer in vitro and in vivo." (PMID 27926503, 2017). "Here, we first showed that FOXD3 knockdown dramatically increased the proliferation of human colon cancer cells, enhanced cell invasive ability and inhibited cell apoptosis." (PMID 27926503, 2017).
colon cancer (continued). "The half maximal inhibitory concentration of inhibitor was markedly higher in FOXD3 knockdown HCT116 colon cancer cells than the normal cells." (PMID 27926503, 2017). "We believed that FOXD3 is likely to be an essential factor in protecting against human colon cancer formation, whose effects are mediated by EGFR-Ras-Raf-MEK-ERK signaling pathway." (PMID 27926503, 2017). "Indeed, 6 out of 10 leading TFs have direct evidence and some experimental validation of their involvement in colon cancer risk and progression: ZNF334, FOXD2, FOXD3, POU3F3, NR1H4, and VSX2." (PMID 41114645, 2025). "As compared to normal tissues, the FOXD3 gene was downregulated in colon cancer tissues, indicating that FOXD3 might play an inhibitory role in the formation of colon cancer." (PMID 37151068, 2023). "The in vitro experiments showed that the downregulation of the FOXD3 gene could inhibit the apoptosis of colon cancer bone metastases, enhance the invasion ability of cells, and significantly increase the proliferation of cells." (PMID 37151068, 2023). "Therefore, the mechanism of FOXD3, inhibiting colon cancer bone metastasis, needs to be further explored." (PMID 37151068, 2023). "Using the combined bioinformatics and cytology experimental analyses, this study aimed to explore the mechanistic role of FOXD3 in the bone metastasis of colon cancer, thereby aiding in the treatment of colon cancer bone metastasis and identification of drug-targeting markers." (PMID 37151068, 2023). "In the current study, in colon cancer bone metastatic cells, the downregulation of the FOXD3 gene could promote cell growth and migration." (PMID 37151068, 2023). "The current study showed that FOXD3 gene knockout could significantly activate the EGFR-RAS-Raf-MEK-ERK signaling pathway in human colon cancer bone metastatic cells." (PMID 37151068, 2023). "Consistent with the CCK8 results, the cell proliferation increased significantly in the Si-FOXD3 group as compared to the control group, indicating that FOXD3 could inhibit the proliferation of colon cancer bone metastatic cells." (PMID 37151068, 2023). "Therefore, this study aimed to evaluate the downregulatory effects of the FOXD3 gene on the proliferation and death of bone metastatic cells in human colon cancer." (PMID 37151068, 2023). "FOXD3 was downregulated in colon cancer and could interact with multiple DEGs in colon cancer bone metastases." (PMID 37151068, 2023). "However, the underlying mechanisms of this signaling pathway and the role of the FOXD3 gene in colon cancer bone metastasis are still unclear." (PMID 37151068, 2023). "FOXD3 gene knockdown could increase the proliferation of human colon cancer bone metastatic cells and their invasive ability." (PMID 37151068, 2023). "While available data indicate that loss of FoxD3 due to epigenetic silencing promotes overexpression of the DCLK1-S variant in human colon cancer cells, no such data exist in non-cancer models." (PMID 34226497, 2021). "Previous literature has reported that the transcription factor Foxd3 could activate miR-214 in human colon cancer cells." (PMID 31959866, 2020). "First, forkhead box D3 (FOXD3) was found to be a suppressor of colon cancer formation." (PMID 30987631, 2019). "In addition, the molecular mechanism by which FOXD3 play its role in colon cancer was studied in vitro and in vivo." (PMID 27926503, 2017). "Thus, it is plausible that FOXD3 is a potential tumor suppressor in human colon cancer progression and represents a promising clinical prognostic marker and therapeutic target for this disease." (PMID 27926503, 2017). "It is proposed that FOXD3 may have potential as a new therapeutic target in human colon cancer treatment." (PMID 27926503, 2017). "Moreover, we demonstrated that silencing FOXD3 in human colon cancer cells markedly activated EGFR/Ras/Raf/MEK/ERK signal pathway." (PMID 27926503, 2017).
colon cancer (continued). "Similarly, in colon cancer, we found that FOXD3 knockdown promoted cell migration and induced mesenchymal attributes." (PMID 27926503, 2017). "Silencing FOXD3 markedly activated EGFR/Ras/Raf/MEK/ERK pathway in human colon cancer cells." (PMID 27926503, 2017). "In this study, we showed that FOXD3 worked as a suppressor for colon cancer formation." (PMID 27926503, 2017). "However, little information is available concerning the role of FOXD3 in influencing colon cancer formation." (PMID 27926503, 2017). "Thus, knockdown of FOXD3 significantly decreased the apoptosis of colon cancer cells compared with the controls." (PMID 27926503, 2017). "The conditional knockout mice will be a useful model to discuss the role of FOXD3 in colon cancer." (PMID 27926503, 2017). "Downregulation of FOXD3 levels by promoter methylation in colon cancer might provide a favorable setting for either acquisition of a BRAF mutation or proliferation by RAS-RAF-MEK over-activation, similar to IGFBP7." (PMID 23324568, 2013). "Moreover, in publicly available clinical tumor expression data sets, we noted that FOXD3 was down-regulated in colon cancer and cervix cancer, while was up-regulated in renal cancer and endometrial cancer." (PMID 24269992, 2013). "Therefore, the FOXD3 gene might act as a tumor suppressor in the development of human colon cancer bone metastases, thereby indicating its potential as a therapeutic target." (PMID 37151068, 2023). "In addition, the downregulation of the FOXD3 gene in colon cancer bone metastatic cells could also affect the EGFR/ERK signaling pathway and alter the expression levels of EMT-related proteins." (PMID 37151068, 2023). "Therefore, it was suggested that the FOXD3 gene could inhibit the occurrence and progression of colon cancer bone metastatic cells by regulating the EGFR/ERK signaling pathway." (PMID 37151068, 2023). "Moreover, the downregulation of the FOXD3 gene could also promote the proliferation of LoVo cells, a colon cancer bone metastasis cell line." (PMID 37151068, 2023). "Overall, this study demonstrated that the downregulation of the FOXD3 gene might promote the proliferation of colon cancer bone metastatic cell lines through the EGFR/ERK pathway and promote their migration through EMT, thereby serving as a promising therapeutic target." (PMID 37151068, 2023). "The results showed that the expression of FOXD3 was markedly increased in NCM460 cells than that in HCT116 and Caco-2 colon cancer cells." (PMID 27926503, 2017). "During western blot of MMP13 in various colon cancer cell lines, active forms of MMP13 could be seen in all three (HCT116, RKO, CT-26) cell lines along with DCLK1-S while FoxD3 levels were minimally detected." (PMID 40839695, 2025). "In human colon cancer tissues, immuno histochemistry staining was used to measure the level of FOXD3 expression." (PMID 27926503, 2017). "77.8% colon cancer tissues showed negative staining for FOXD3, while 78.6% normal tissues showed obvious positive staining." (PMID 27926503, 2017). "FOXD3 could inhibit the cellular invasion and EMT process in colon cancer bone metastases." (PMID 37151068, 2023). "Finally, this study only analyzed the effects of FOXD3 on the proliferation of colon cancer bone metastasis cells and did not further investigate the genes related to colon cancer bone metastasis." (PMID 37151068, 2023). "However, there are no studies on the effects of the FOXD3 gene on the bone metastases of colon cancer." (PMID 37151068, 2023). "FOXD3 gene knockdown could activate the expression of EGFR/ERK signaling pathway-related proteins and inhibit/promote the expression of EMT-related proteins, which in turn promoted the proliferation and metastasis of LoVo cells from colon cancer bone metastases." (PMID 37151068, 2023).
colon cancer (continued). "Therefore, this study suggested that the FOXD3 gene might inhibit the development of EMT and regulate the proliferation of colon cancer bone metastasis cells through the EGFR-RAS-Raf-MEK-ERK signaling pathway, thereby exhibiting a potential for novel future therapies." (PMID 37151068, 2023).
gastric cancer (12 papers, 2013 to 2026). A primary or metastatic malignant neoplasm involving the stomach. "The proapoptotic effect of quercetin on cisplatin chemotherapy resistance in gastric cancer is associated with increased FOXD3 levels." (PMID 39795061, 2024). "Both gain- and loss-of-function studies have demonstrated that FOXD3 significantly inhibits the growth and invasion of gastric cancer cells." (PMID 24269992, 2013). "Functional studies show that restoring FOXD3 expression suppresses gastric cancer cell proliferation, invasion, and tumor growth in xenograft models, in part by promoting apoptosis." (PMID 41486167, 2026). "Hypermethylation of the FOXD3 promoter occurs both in mice and human tumors and correlates with decreased survival in patients with gastric cancer." (PMID 41486167, 2026). "Once reactivated, FOXD3 inhibits gastric cancer cell proliferation and reduces the growth of tumors in mice infected with Hp by promoting tumor cell apoptosis." (PMID 35163679, 2022). "Demethylation of a panel of gastric cancer cell lines with the DNA methyltransferase 5-aza-2′-deoxycytidine reactivates FOXD3 expression." (PMID 35163679, 2022). "In conclusion, FOX family paly critical roles in gastric cancer, and FOXO4 and FOXD3 were identified as independent prognostic factors for survival outcomes of gastric cancer." (PMID 27027443, 2016). "In the TCGA cohort, FOXO4 (HR = 0.613, 95%CI 0.452–0.832) and FOXD3 (HR = 1.704, 95%CI 1.212–2.397) were shown independently predictive of overall survival in gastric cancer after Cox proportional hazards analysis." (PMID 27027443, 2016). "In gastric cancer, the expression of FOXD3 is down-regulated mainly due to the hypermethylation of promoter and FOXD3 expression is correlated with survival time of patients." (PMID 26011451, 2015). "Genome-wide location analysis has identified many proapoptotic genes as the potential transcriptional targets of FOXD3 in mice and humans gastric cancer." (PMID 26011451, 2015). "Both over-expression and knockdown of FOXD3 studies have demonstrated that FOXD3 significantly inhibits the proliferation, metastasis and invasion of breast and gastric cancer cells." (PMID 26011451, 2015). "In agreement, FOXD3 was repressed in various gastric cancer cell lines and in more than 80% of gastric cancer cases." (PMID 24133496, 2013). "In gastric cancer specimens and cell lines, FOXD3 is under-expressed due to the promoter hypermethylation, and is correlated with survival time of patients with gastric cancer." (PMID 24269992, 2013). "Over-expression of FOXD3 significantly inhibits the proliferation and invasion of gastric cancer cells in vitro and in vivo, at least partially, by promoting the apoptosis of cancer cells." (PMID 24269992, 2013). "Genome-wide location analysis has identified many proapoptotic genes as the potential transcriptional targets of FOXD3 in gastric cancer." (PMID 24269992, 2013). "Gastric cancer patients with hypermethylated FOXD3 survived a shorter time than other patients." (PMID 30781778, 2019). "Elevated FOXD3 significantly inhibited gastric cancer progression." (PMID 28430585, 2017). "In univariate Cox proportion hazard ratio analysis, age, tumor(T) stage, Node(N) stage, metastasis(M) stage, FOXD3, FOXO4 and FOXS1 expression were significantly associated with prognosis in terms of OS of patients with gastric cancer in the TCGA cohorts (p < 0.05)." (PMID 27027443, 2016). "Promoter hypermethylation could slicing FOXD3 expression and significantly promotor gastric cancer cell proliferation and invasion." (PMID 27027443, 2016). "Furthermore, FOXD3 significantly inhibits the proliferation and invasion of gastric cancer cell lines." (PMID 26011451, 2015). "FOXD3-activated transcription of cell-death-regulating genes RARB and CYFIP2, and induction of overexpression of FOXD3 significantly inhibited gastric cancer cell proliferation, facilitating tumor cell apoptosis." (PMID 30781778, 2019).
gastric cancer (continued). "Collectively, FOX family paly critical roles in gastric cancer, and FOXO4 and FOXD3 were identified as independent prognostic factors for survival outcomes of gastric cancer." (PMID 27027443, 2016). "Members of this family, especially FOXO4 and FOXD3, are two independent prognostic factors for OS and DFS of gastric cancer patients." (PMID 27027443, 2016). "Several studies have shown that epigenetic inactivation of FOXD3 by promoter methylation during the development of CLL, colorectal and gastric cancer." (PMID 26011451, 2015). "In our set of genes, FOXD3 and FOXF2 have had a few studies performed on colon or gastric cancers." (PMID 30987631, 2019).